C7orf25 (chromosome 7 open reading frame 25)
Synonyms: MGC2821
Tractability: PROTAC: ubiquitination databases record sites on it; its protein half-life has been measured.
Gene: Protein-coding gene on chromosome 7 (42,908,619 to 42,912,518, reverse strand). Ensembl gene ENSG00000136197.
Subcellular location (Human Protein Atlas): Nucleoplasm; Cytosol
Gene Ontology:
Molecular function: protein binding
Cellular component: nucleoplasm
Genetic constraint (gnomAD): Loss-of-function variants: 14 observed, 27.55 expected, observed/expected ratio (o/e) 0.51, 90% interval 0.34 to 0.79. The upper end of that interval is the gene's LOEUF score, 0.79, which puts it in group 3 of 6, group 1 being the genes least tolerant of losing a copy. Missense variants: 405 observed, 522.99 expected, observed/expected ratio (o/e) 0.77, 90% interval 0.71 to 0.84. Synonymous variants: 184 observed, 191.44 expected, observed/expected ratio (o/e) 0.96, 90% interval 0.85 to 1.09.
Homologues: Orthologues: chimpanzee C7H7orf25 (99% identical), macaque C3H7orf25 (99% identical), dog C7orf25 (99% identical), pig C7orf25 (97% identical), guinea pig C7orf25 (97% identical), rabbit C7orf25 (96% identical), mouse AW209491 (93% identical), rat C17h7orf25 (92% identical), tropical clawed frog c6h7orf25 (80% identical), zebrafish C2H7orf25 (72% identical), Drosophila melanogaster CG42553 (32% identical), Caenorhabditis elegans F33G12.3 (27% identical).
Diseases named in the same sentence as C7orf25 in open-access papers:
C7orf25 is named in the same sentence as 3 diseases in open-access papers, as found by Europe PMC text mining. Sharing a sentence is not in itself a finding about the gene and the disease. The quoted sentences say what the papers report.
cancer (1 paper, 2022). A tumor composed of atypical neoplastic, often pleomorphic cells that invade other tissues. "The intersection of OPN3 and the top 500 OPN3-associated genes from the most related modules showed 2 genes (C7orf70 and C7orf25) closely related to the upregulation of OPN3 expression in all 5 types of cancers." (PMID 35180853, 2022). "Therefore, we conducted GSEA to study the molecular mechanisms of OPN3 in carcinogenesis and progression, which demonstrated that OPN3 in 5 types of cancers remarkably correlates with modules of C7orf70 and C7orf25 and the “Ribosome” pathway." (PMID 35180853, 2022). "Furthermore, the enrichment analysis was mainly concentrated in C7orf70, C7orf25 and the “ribosome” pathway by GSEA in 5 types of cancers, indicating that OPN3 might affect tumorigenesis and progression by regulating gene expression and ribosome biogenesis." (PMID 35180853, 2022).
neurological diseases (1 paper, 2023). "Apart from C7orf25, a nuclear protein of an unknown function, the other 10 proteins are implicated in various functions, with several being associated with neurological diseases (and Discussion)." (PMID 36980839, 2023).
C7orf25 also shares sentences with these, for which no sentence is quoted: sarcoidosis (1 paper).